TGFBI (transforming growth factor beta induced)
Diseases named in the same sentence as TGFBI in open-access papers (continued):
Sharing a sentence is not in itself a finding about the gene and the disease.
ovarian carcinoma (continued). "In this study, we examined the methylation status and expression of TGFBI in epithelial ovarian cancer tissues, paclitaxel-sensitive and -resistant ovarian cancer cell lines in order to determine whether the methylation of TGFBI is asscociated with paclitaxel chemoresistance." (PMID 22248469, 2012). "An analysis of bioinformatics data revealed that increased expression of TGFBI led to significant decrease of overall survival (OS), progression-free survival (PFS) and post-progression survival (PPS) in ovarian cancer patients." (PMID 38395907, 2024). "Accordingly, we also found that TGFBI KO in SKOV3 and Caov-3 cells led to decreased expression of MMP-2, which inferred that TGFBI had the potential of remodeling ECM in ovarian cancer microenvironment." (PMID 38395907, 2024). "The migration assays showed that scratches of TGFBI KO groups healed slowly and the area of cell migration significantly reduced after culture for 24 h for SKOV-3 and Caov-3 ovarian cancer cells." (PMID 38395907, 2024). "Some of the reported hypermethylated genes in ovarian cancer are BRCA1, RASSF1A, TGFBI, DOK1, RUNX3, and CAMK2N1." (PMID 38627856, 2024). "TGFBI an ECM protein, with multiple functions in ovarian cancer is up regulated by TGFβ signaling pathway." (PMID 36463238, 2022). "Among the identified proteins, significant enhanced expression of GFPT2, FLNA, TGFBI (CDGG1), ITGA2 predicted unfavorable prognosis in ovarian cancer patients." (PMID 36463238, 2022). "In the present study we identified TGFBI, TNC, and FN1 as potential mediators of TAM-induced ovarian cancer migration, underscoring the known role of ECM proteins in tumor progression." (PMID 32312959, 2020). "Although ovarian cancer cells such as PEO1 express and secrete both TGFBI and SPARC, while SKOV3 primarily only express TGFBI, their extracellular matrix is not well organized and the TGFBI fibrillar deposition is almost non-existent." (PMID 27622658, 2016). "The extracellular matrix (ECM) has a key role in facilitating the progression of ovarian cancer and we have shown recently that the secreted ECM protein TGFBI modulates the response of ovarian cancer to paclitaxel-induced cell death." (PMID 22640878, 2012). "However, the role of TGFBI methylation in paclitaxel chemoresistance in ovarian cancer is unknown." (PMID 22248469, 2012). "Thus, for ovarian cancer cells, it appears neither Syndecan-1 nor Syndecan-4 is necessary for adhesion to TGFBI, nor does the loss of Syndecan-4 synergize with αvß3 to stimulate adhesion to TGFBI." (PMID 22640878, 2012). "In contrast, only sparsely methylated or unmethylated CpG sites were identified in cell lines with a rich level of TGFBI expression, including SKOV3, A2780, OVCAR8, and SKOV3/DDP ovarian cancer cell lines." (PMID 22248469, 2012). "Intriguingly, TGFBI derived from non-cancer cells such as TAM in ovarian cancer also promotes cell invasion and metastasis." (PMID 36906534, 2023). "The use of TGFBI methylation as novel epigenetic biomarker for discriminating ovarian cancer from non-cancer or borderline tumors should be further explored." (PMID 22949874, 2012). "ECM-related genes (ρ = 0.56, 95%CI: 0.48–0.62, p < 0.01) and degradation of ECM (ρ = 0.61, 95%CI: 0.54–0.67, p < 0.01) were also significantly positively correlated with TGFBI expression, suggesting that TGFBI might regulate ECM remodeling in ovarian cancer microenvironment." (PMID 38395907, 2024). "Since our bioinformatic results revealed that TGFBI expression was positively correlated with the levels of EMT markers and ECM-related genes, we inferred that TGFBI might be involved in EMT reprogram and ECM remodeling in ovarian cancer." (PMID 38395907, 2024). "However, Cox proportional hazard analysis showed the high TGFBI expression was negatively correlated with OS in TCGA ovarian cancer cohort, and its expression had no significant predictive power of platinum sensitivity in IHC verification." (PMID 34888242, 2021).
ovarian carcinoma (continued). "However, because 1 ovarian cancer tissue lacking TGFBI mRNA expression was not methylated, we presume that mechanisms of inactivating the gene other than methylation must exist." (PMID 22248469, 2012). "Although TGFBI has been shown to signal through multiple integrin heterodimeric receptors, the predominant signaling pathways and the relationship to other ECM components in ovarian cancer is unknown." (PMID 22640878, 2012). "Our results suggest that the RGD motif of full-length TGFBI is necessary, but not sufficient, for ovarian cancer cell adhesion, thus indicating it may cooperate with flanking residues or other motifs, potentially present within the fourth Fasciclin I domain to mediate this process." (PMID 22640878, 2012). "The RGD motif present in the carboxy-terminus of TGFBI is necessary, but not sufficient, for SKOV3 cell adhesion and is dispensable for adhesion of ovarian cancer cells lacking ß3 integrin expression." (PMID 22640878, 2012). "In contrast to TGFBI, the carboxy-terminus of periostin, lacking a RGD motif, is unable to support adhesion of ovarian cancer cells." (PMID 22640878, 2012).
breast carcinoma (45 papers, 2009 to 2025). "TGFBI hypermethylation in primary tumors is substantially associated with trastuzumab resistance in patients with HER2+ breast cancer." (PMID 40843360, 2025). "For instance, trastuzumab-resistant HER2-positive breast cancer was found associated with downregulated TGFBI, CXCL2, and SLC38A1, which was silenced by DNA hypermethylation." (PMID 40464376, 2025). "Corresponding to the poor prognosis of TGFBI expression, TGFBI methylation was associated with the good prognosis of breast cancer." (PMID 38245723, 2024). "Through bioinformatics analysis, we found that higher expression of TGFBI was associated with shorted lung metastasis-free survival, relapse-free survival, disease-free survival, and overall survival of breast cancer." (PMID 38245723, 2024). "The associations of TGFBI with ER status in breast cancer patients were further validated using EMBL-EBI, GEO, and TCGA-BRCA datasets." (PMID 38245723, 2024). "Corresponding with a poor prognosis of TGFBI expression, TGFBI methylation was associated with a good prognosis of breast cancer." (PMID 38245723, 2024). "In E-MTAB-365, GSE21653, and GSE25066 datasets, higher expression of TGFBI was associated with the shorted relapse-free survival of breast cancer." (PMID 38245723, 2024). "So, we used as many breast cancer cohorts and tissue microarrays to get a more precise conclusion that higher expression of TGFBI was associated with short overall survival of breast cancer." (PMID 38245723, 2024). "On the contrary, we showed that TGFBI was highly expressed in metastatic breast cancer cells and associated with higher lung metastasis of breast cancer." (PMID 38245723, 2024). "TGFBI promoter CpG island hypermethylation is also associated with trastuzumab resistance in HER2-positive breast cancer patients." (PMID 37174034, 2023). "In contrast, high TGFBI expression was associated with better OS in blood cancer (p = 0.016), breast cancer (p = 0.045), and esophageal cancer (p = 0.047)." (PMID 34671645, 2021). "Taken together, these results indicate that TGFBI expression predicts tumour aggressiveness and poorer outcomes in human breast cancer, and it is associated with higher macrophage infiltration and angiogenesis." (PMID 33080107, 2020). "In primary tumors, TGFBI hypermethylation was significantly associated with trastuzumab resistance in HER2+ breast cancer patients." (PMID 31277676, 2019). "TGFBI activates adhesion-associated signaling and decreases the motility in breast cancer cells both in vitro and in vivo." (PMID 23236365, 2012). "In this study, ectopic expression of TGFBI was used to ascertain its role as a tumor suppressor and to determine the underlying mechanism of mesothelioma and breast cancer." (PMID 22695319, 2012). "However, in the TCGA-BRCA dataset, higher expression of TGFBI was associated with the shorted overall survival of breast cancer." (PMID 38245723, 2024). "Also, the stromal scores as well as the immune scores of breast cancer were associated with TGFBI expression levels." (PMID 38245723, 2024). "Moreover, in GSE4922, GSE45255, and GSE58644 datasets, higher expression of TGFBI was associated with the shorted disease-free survival of breast cancer." (PMID 38245723, 2024). "Also, in those 404 breast cancer patients, TGFBI higher expression was associated with the higher probability of lung metastasis." (PMID 38245723, 2024). "In addition, downregulated TGFBI, acting as a tumor suppresser, can cause tumor growth in breast cancer, lung cancer, and mesothelioma." (PMID 34671645, 2021). "It has been reported that TGFBI is associated with both breast cancer inhibition and progression." (PMID 33138797, 2020). "Furthermore, human data mining in a cohort of breast cancer patients showed that higher expression of TGFBI correlates with poor prognosis and is associated with the more aggressive subtypes of breast cancer." (PMID 33080107, 2020).
breast carcinoma (continued). "In melanoma, mesothelioma, and breast cancer, TGFBI overexpression suppressed proliferation and malignant potential; however, targeting TGFBI may be associated with an increased risk of chemo-resistance in these patients." (PMID 28106769, 2017). "TGFβ-induced gene TGFBI was correlated with the prognosis and immune infiltrations of breast cancer." (PMID 38245723, 2024). "In 88 TGFBI highly expressed breast cancer patients, the percentage of ER + was 37.8 ± 4.4, while, in 48 TGFBI lowly expressed breast cancer patients, the percentage of ER + was 59.58 ± 5.8." (PMID 38245723, 2024). "Overall, we highlighted that TGFβ induced gene TGFBI was correlated with the prognosis and immune infiltrations of breast cancer." (PMID 38245723, 2024). "Based on TGFBI expression levels, breast cancer patients were classified into the TGFBI high expression sub-group and the TGFBI low expression sub-group." (PMID 38245723, 2024). "Like TGFβ, TGFBI also affects the infiltrations of immune cells to generate a suitable tumor microenvironment for breast cancer cell metastasis." (PMID 38245723, 2024). "In total, the expressions of TGFBI in 139 Chinese breast cancer tissues were analyzed by immunohistochemistry." (PMID 38245723, 2024). "In HER2-positive breast cancer cells, hyper-methylation mediated the low TGFBI expression and the induction of Herceptin resistance." (PMID 38245723, 2024). "The stromal score, immune score, and the infiltrations of immune cells were also correlated with TGFBI expression in breast cancer." (PMID 38245723, 2024). "Compared with non-metastatic breast cancer cells MDA-MB-453, MCF7, T47D, HCC202, and BT-474, the expression levels of TGFBI were higher in metastatic breast cancer cells BT-549, MDA-MB-231, DU-4475, and Hs-578-T." (PMID 38245723, 2024). "TGFBI was correlated with the score of the TGFβ signaling pathway and multiple immune-related signaling pathways in breast cancer." (PMID 38245723, 2024). "TGFBI is identified as one of the hub genes for potential prognostic relevance of breast cancer by conducting weighted gene co-expression network analysis and univariate Cox regression." (PMID 38302910, 2024). "Compared with breast cancer patients with lower TGFBI expressions, 1253 genes were differentially expressed in breast cancer patients with higher TGFBI expressions in TCGA-BRCA dataset based on the thresholds of P value < 0.001 and fold change > 1.5." (PMID 38245723, 2024). "The prognosis of the induced gene (TGFBI) in breast cancer was determined through bioinformatics analysis and validated using tissue microarray." (PMID 38245723, 2024). "We found that high expression of TGFBI was correlated with the poor prognosis of breast cancer patients." (PMID 38245723, 2024). "The prognosis of TGFBI in breast cancer was further validated using multiple independent breast cancer cohorts from the European Bioinformatics Institute (EMBL-EBI), GEO, and TCGA datasets." (PMID 38245723, 2024). "Even more relevant is that epigenetic silencing of TGFBI was found to confer resistance to trastuzumab in human breast cancer." (PMID 37367744, 2023). "High TGFBI expression accompanies tumor resistance, and it promotes breast cancer metastasis by modulating tumor hypoxia." (PMID 35741755, 2022). "Fico and Santamaria‐Martínez found that TGFBI induced breast cancer metastasis by regulating the TME and hypoxia." (PMID 34484333, 2021). "An up-regulation of TGFBI can promote the occurrence and metastasis of breast cancer, increase tumor angiogenesis and increase hypoxia, and TGFBI overexpression promotes oral squamous cell carcinoma." (PMID 34217310, 2021). "TGFBI (transforming growth factor beta induced) has been reported to be an oncogene in a variety of cancers including prostate, ovarian, and breast cancer." (PMID 34484333, 2021). "Overall, these results indicate that TGFBI promotes aberrant angiogenesis and increases tumour hypoxia in breast cancer." (PMID 33080107, 2020).
breast carcinoma (continued). "In breast cancer research, distant metastases tend to develop when TGFBI and CD44 were expressed at high levels, which verifies the relationship between TGFBI and immune responses." (PMID 33614494, 2020). "In order to understand the relevance of TGFBI in human breast cancer, we performed in silico analysis using the METABRIC cohort and found that TGFBI predicts poor prognosis." (PMID 33080107, 2020). "Here, we aimed at clarifying the niche‐supporting role of the ECM protein transforming growth factor beta induced (TGFBI) in breast cancer." (PMID 33080107, 2020). "In search for microenvironmental factors supporting cancer stem cell (CSC) growth and tumour progression to metastasis, we here investigated the role of the matricellular protein transforming growth factor beta induced (TGFBI) in breast cancer." (PMID 33080107, 2020). "In summary, our study reveals a new biological role for the matricellular protein TGFBI in breast cancer." (PMID 33080107, 2020). "Whereas, in mesothelioma and breast cancer cells, TGFBI suppress cell proliferation, delay G1-S phase transition, and induces death." (PMID 30379886, 2018). "We here present strong evidence that unequivocally supports that TGFBI exhibits an inhibitory effect on tumor growth both in vitro and in vivo, especially in mesothelioma and breast cancer cells." (PMID 22695319, 2012). "Collectively, these results imply that TGFBI plays a suppressive role in the development of mesothelioma and breast cancer cells, possibly through inhibitions of cell proliferation, delaying of G1-S phase transition, and induction of senescence." (PMID 22695319, 2012). "TGFBI expression inhibited anchorage-independent growth in these two cancer cell lines, exhibiting a drop of 48.54% in mesothelioma cells and 90.89% in breast cancer cells relative to control cells of both types." (PMID 22695319, 2012). "Moreover, the correlations of TGFBI with lung metastasis of breast cancer were further determined using Kaplan–Meier survival analysis." (PMID 38245723, 2024). "Moreover, in “TIMER” database, the macrophages infiltrations were most correlated with TGFBI expressions in breast cancer patients." (PMID 38245723, 2024). "Furthermore, in TCGA-BRCA, GSE37754, and GSE78758 datasets, hypo-methylation of TGFBI was correlated with the shorted overall survival of breast cancer." (PMID 38245723, 2024). "Correspondingly, breast cancer patients with higher TGFBI methylation had higher overall survival." (PMID 38245723, 2024). "So, we tested the correlations between TGFBI and immune infiltrations of breast cancer." (PMID 38245723, 2024). "Therefore, E0771 murine breast cancer cells were used for subsequent experiments because they expressed high Cat D and low TGFBI levels." (PMID 38297161, 2024). "Moreover, the functions and downstream mechanisms of TGFBI in lung metastasis of breast cancer were revealed in our study." (PMID 38245723, 2024). "TGFBI was correlated with the prognosis and immune infiltrations of breast cancer." (PMID 38245723, 2024). "Furthermore, we analyzed the expressions of TGFBI in breast cancer patients with different ER and PR statuses and found that TGFBI was associated with ER and PR expressions in breast cancer." (PMID 38245723, 2024). "TGFBI could inhibit the growth of breast cancer cells and suppress breast cancer metastasis by inhibiting matrix metalloproteinase activity." (PMID 38245723, 2024). "First, the expressions of TGFBI were analyzed in various breast cancer cell lines." (PMID 38245723, 2024). "Breast cancer patients with low expression of TGFBI had significantly longer overall survival." (PMID 38245723, 2024). "Furthermore, in E-MTAB-365, GSE20685, GSE58644 and GSE158309 datasets, the infiltrations of macrophages were all statistically correlated with TGFBI expressions in breast cancer patients." (PMID 38245723, 2024). "Chinese breast cancer patients with higher TGFBI expression had lower overall survival." (PMID 38245723, 2024).